NKAIN2 (sodium/potassium transporting ATPase interacting 2)
Synonyms: FAM77B; TCBA1; NKAIP2; TCBA
Tractability: Antibody: UniProt places it where antibodies can reach, with high confidence; UniProt predicts a signal peptide or a membrane-spanning region; its Gene Ontology location is reachable by antibodies, with medium confidence.
Gene: Protein-coding gene on chromosome 6 (123,803,865 to 124,825,640, forward strand). Ensembl gene ENSG00000188580.
Subcellular location: Cell membrane
Subcellular location (Human Protein Atlas): Cytosol
Gene Ontology:
Biological process: regulation of sodium ion transport
Cellular component: plasma membrane
Genetic constraint (gnomAD): Loss-of-function variants: 5 observed, 11.63 expected, observed/expected ratio (o/e) 0.43, 90% interval 0.22 to 0.9. The upper end of that interval is the gene's LOEUF score, 0.9, which puts it in group 3 of 6, group 1 being the genes least tolerant of losing a copy. Missense variants: 88 observed, 114.06 expected, observed/expected ratio (o/e) 0.77, 90% interval 0.65 to 0.92. Synonymous variants: 34 observed, 41.62 expected, observed/expected ratio (o/e) 0.82, 90% interval 0.62 to 1.09.
Homologues: Orthologues: chimpanzee NKAIN2 (100% identical), macaque NKAIN2 (100% identical), dog NKAIN2 (99% identical), pig NKAIN2 (99% identical), rabbit NKAIN2 (99% identical), guinea pig NKAIN2 (98% identical), mouse Nkain2 (98% identical), rat Nkain2 (92% identical), zebrafish nkain2 (87% identical), tropical clawed frog nkain2 (80% identical), Drosophila melanogaster NKAIN (44% identical), Caenorhabditis elegans gldi-7 (27% identical). Paralogues in human: NKAIN1 (70% identical), NKAIN3 (60% identical), NKAIN4 (59% identical).
Diseases named in the same sentence as NKAIN2 in open-access papers:
NKAIN2 is named in the same sentence as 24 diseases in open-access papers, as found by Europe PMC text mining. Sharing a sentence is not in itself a finding about the gene and the disease. The quoted sentences say what the papers report.
developmental delay (2 papers, 2015 to 2016). "Truncation of NKAIN2 has been described in patients with developmental delay and complex neurological impairment." (PMID 25637059, 2015).
neuroblastoma (2 papers, 2013 to 2016). Neuroblastoma (NB) is the most common solid, extracranial childhood tumor. "While the oncogenic function of this chimeric gene has not been recognized, a copy number gain and increased expression of NKAIN2 were found in a study of neuroblastoma, suggesting that NKAIN2 can also act as an oncogene." (PMID 27588475, 2016).
prostate carcinoma (2 papers, 2016 to 2022). A carcinoma that arises from epithelial cells of the prostate gland. "Somatic mutations of NKAIN2 in prostate cancer samples exist but at very low frequency, suggesting that it is a putative tumor suppressor gene (TSG) with haploid insufficiency." (PMID 27588475, 2016). "According to results from this study, chromosomal deletion and truncation are the two main genomic mechanisms leading to NKAIN2 loss of function in prostate cancer, whereas mutation of NKAIN2 occurs in prostate cancer at a low frequency." (PMID 27588475, 2016). "Although NKAIN2 mutations were found in many types of cancers, its low frequency is consistent with our data in prostate cancer." (PMID 27588475, 2016). "Recurrent chromosome breakpoints at 6q22.31, leading to truncation and potential loss-of-function of the NKAIN2 gene, in Chinese prostate cancer patients were previously identified." (PMID 27588475, 2016). "Identification of prostate cancer cases with loss of NKAIN2 functions, and treating them with Na+/K+-ATPase inhibitors with or without combination with other therapeutic drugs may provide an efficient therapeutic approach." (PMID 27588475, 2016). "We demonstrated that loss of NKAIN2 function occurs in a large proportion of prostate cancer cases, which may lead to overactivity of Na+/K+-ATPase and consequently prostate cancer development and progression." (PMID 27588475, 2016). "Our recent SNP array analysis revealed that genomic truncations are a common mechanism disrupting TSGs in prostate cancer and NKAIN2 gene is more frequently detected in prostate cancers from Chinese than UK men." (PMID 27588475, 2016). "Conversely, knockdown of NKAIN2 promotes prostate cancer cell growth by inhibiting cell apoptosis, and increasing cell migration and invasion." (PMID 27588475, 2016). "According to this and our previous study, genomic truncation of NKAIN2 gene occurs mainly in Chinese and rarely in UK prostate cancer samples." (PMID 27588475, 2016). "We confirmed that NKAIN2 is a frequently down-regulated gene in prostate cancer, particularly in Chinese cases, and found that it suppresses prostate cancer cell growth and invasion, suggesting its role as a novel putative TSG." (PMID 27588475, 2016). "By overexpression and knockdown of NKAIN2 in prostate cancer cells, we demonstrated that it suppresses cancer cell growth, induces apoptosis and inhibits cell migration and invasion." (PMID 27588475, 2016). "NKAIN2 truncation and deletion events were detected in 9/140 (6.4%) and 46/134 (34.3%) Chinese prostate cancer cases, respectively." (PMID 27588475, 2016). "Subsequent examination of NKAIN2 protein expression by immunohistochemistry in 281 prostate cancer cases, including 161 cases from China and 120 cases from UK, revealed significant under-expression when compared to the adjacent normal tissues (p < 0.0001)." (PMID 27588475, 2016). "This is consistent with the report that NKAIN2 was down-regulated in castration resistance prostate cancer samples." (PMID 27588475, 2016). "Further investigations are required to understand how NKAIN2 suppresses Na+/K+-ATPase functions and by which molecular pathways NKAIN2 restrains prostate cancer development and/or progression." (PMID 27588475, 2016). "Fluorescence in situ hybridization analysis confirmed that NKAIN2 truncation is specific to Chinese while deletion of the gene is frequent in both Chinese and UK prostate cancers." (PMID 27588475, 2016). "In this study we investigated genomic, methylation and expression changes of NKAIN2 in a large number of prostate cancer samples and determined its functional role in prostate cancer cells." (PMID 27588475, 2016). "Given that 6q deletions covering this genomic region are common in many human cancers, including prostate cancer, NKAIN2 is a potential TSG." (PMID 27588475, 2016).
prostate carcinoma (continued). "Our functional studies showed that overexpression of NKAIN2 in prostate cancer cells inhibits cellular growth by promoting cell apoptosis, and decreasing cell migration and invasion." (PMID 27588475, 2016). "In conclusion, we found that NKAIN2 is commonly inactivated in prostate cancer, particularly in the Chinese cases, by genomic deletion and truncation." (PMID 27588475, 2016). "NKAIN2 is known as a tumor suppressor in Chinese prostate cancer." (PMID 35439935, 2022). "In addition to our data showing that NKAIN2 is commonly inactivated by chromosome alterations in prostate cancer, low mRNA expression of NKAIN2 has been reported in castration-resistant prostate cancer." (PMID 27588475, 2016). "However, in prostate cancer, all previous studies and our data provided complementary evidences that NKAIN2 is a potential TSG." (PMID 27588475, 2016). "siRNA knockdown of NKAIN2 was employed to explore the TSG role of NKAIN2 and its potential cellular function in 22RV1 and PC3 prostate cancer cells." (PMID 27588475, 2016). "Consistent with our earlier study, NKAIN2 gene deletion events were detected at a similar frequency in prostate cancer cases taken from the UK (21/89, 23.2%) and China (no statistical significance: p = 0.10)." (PMID 27588475, 2016). "Nevertheless, since the tumor suppression effects were observed by increasing and decreasing NKAIN2 expression level in the AR negative PC3 cells, NKAIN2 can clearly suppress prostate cancer cell growth and migration in cells without androgen activity." (PMID 27588475, 2016).
alcohol dependence (1 paper, 2022). Physical and psychological dependence on alcohol. "Previous study also revealed the strong association of NKAIN2 with alcohol dependence and nicotine dependence." (PMID 36539828, 2022).
Insulin resistance (1 paper, 2025). Increased resistance towards insulin, that is, diminished effectiveness of insulin in reducing blood glucose levels. "GWIS identified ten SNPs in three loci, including rs4713207 (OR14J1, Pmeta = 3.95 × 10−8) for insulin resistance, rs17708475 (NKAIN2, Pmeta = 4.83 × 10−8) for insulin sensitivity, and rs201613 (MYH3, Pmeta = 1.05 × 10−8) for disposition index." (PMID 40719081, 2025).
leukemia (1 paper, 2016). A malignant (clonal) hematologic disorder, involving hematopoietic stem cells and characterized by the presence of primitive or atypical myeloid or lymphoid cells in the bone marrow and the blood. "All chromosomal rearrangements with breakpoints at NKAIN2 reported to date in other human malignancies, including neurofibromas, T-cell lymphoma and leukemia, were found in East Asian patients." (PMID 27588475, 2016).
major depression (1 paper, 2018). "Previous studies have shown that NKAIN2 may be related to neurological phenotypes such as major depression." (PMID 29341862, 2018).
neurofibroma (1 paper, 2016). An intraneural or extraneural neoplasm arising from nerve tissues and neural sheaths. "In neurofibromas, sub-microscopic deletions containing NKAIN2 were detected by microarray in 5 of 9 samples." (PMID 27588475, 2016).
Obesity (1 paper, 2018). Accumulation of substantial excess body fat. "Given that pathophysiological mechanisms are shared between some neurodegenerative disorders and obesity, rs9491140 of NKAIN2 may be associated with BMI, although the functional relevance remain unclear." (PMID 29341862, 2018).
schizophrenia (1 paper, 2023). A major psychotic disorder characterized by abnormalities in the perception or expression of reality. "Previous studies have shown that NKAIN2 may be related to neurological phenotypes, such as schizophrenia and bipolar disease, as well as being a susceptibility locus for BMI." (PMID 38162683, 2023).
cancer (5 papers, 2013 to 2021). A tumor composed of atypical neoplastic, often pleomorphic cells that invade other tissues. "NKAIN2 expression was reduced in 25 cancer cases when compared to matched normal controls, and overall expression was significantly lower in cancer than in the adjacent normal samples (p = 0.002)." (PMID 27588475, 2016). "NKAIN2 may act as a tumor suppressor involved in inhibition of cancer cell growth, migration and invasion as well as inducement of apoptosis, potentially through suppressing Na+/K+-ATPase or other molecular pathways." (PMID 27588475, 2016). "Therefore, NKAIN2 may suppress cancer cell growth, migration and invasion, and induce apoptosis by inhibiting Na+/K+-ATPase activity through binding with its beta-subunit." (PMID 27588475, 2016).
tumor (5 papers, 2013 to 2022). "Further investigations of other downstream mechanisms associated with the tumor suppressor activity of NKAIN2 have the potential to identify more molecular targets for the development of novel therapies, which can be used alone or in combination with Na+/K+-ATPase inhibitors." (PMID 27588475, 2016). "One of these genes, NKAIN2, was detected upregulated in a large cohort of NB patients (both tumor and blood speciments) and NB cell lines with aggressive phenotype, suggesting its putative role in NB pathogenesis." (PMID 24205241, 2013). "We provided evidence that NKAIN2 play a role in NB development because its expression is directly related with the aggressiveness of human NB cell lines and tumor specimens and it is downregulated during ATRA differentiation." (PMID 24205241, 2013). "mRNA expression of NKAIN2 was analyzed by QRT-PCR in 36 paired tumor and adjacent normal prostate tissue samples from Chinese patients." (PMID 27588475, 2016). "To investigate how NKAIN2 expression may contribute to tumor initiation and/or clinical phenotype, we next evaluated NKAIN2 mRNA levels on several NB cell lines without copy number changes at 6p, in order to avoid the influence of somatic DNA alterations on gene expression." (PMID 24205241, 2013).
NKAIN2 also shares sentences with these, for which no sentence is quoted: adenocarcinoma (1 paper); Anxiety (1); gastric cancer (1); insomnia (1); neurodegenerative disease (1); neurological disorders (1); nicotine dependence (1); non-small cell lung carcinoma (1); pancreatic cancer (1); renal cell carcinoma (1); skin malignant melanoma (1); T-cell lymphoma (1).